INS (insulin)
Diseases named in the same sentence as INS in open-access papers (continued):
Sharing a sentence is not in itself a finding about the gene and the disease.
diabetes (continued). "Models were trained for sex, age, BMI, insulin sensitivity, HbA1c, and prediabetes or incident diabetes." (PMID 34591793, 2021). "The discovery that α-cells can be efficiently reprogrammed into insulin-secreting cells in mice and humans has opened promising avenues for innovative diabetes therapies." (PMID 34340653, 2021). "Total pancreatectomy by itself results in post-pancreatectomy diabetes, but with islet engraftment and function, both alpha and beta cells allow the patient the potential to secrete endogenous glucagon and insulin, respectively, over time." (PMID 34064129, 2021). "Differentially methylated genes of m6A are enriched in insulin regulatory and diabetes-related metabolic pathways and several genes in the insulin/IGF1-AKT-PDX1 signal transduction pathway displayed reduced methylation levels." (PMID 34950107, 2021). "In this review, different transdermal insulin delivery techniques and their improvements for diabetes care are highlighted." (PMID 33466845, 2021). "Alloxan, a known hyperglycemic agent induces diabetes by inhibition of glucose-mediated insulin secretion as well as induction of oxidative damage to pancreatic β-cells (insulin-producing cells in islets of Langerhans)." (PMID 34209371, 2021). "CVDs and diabetes medicine dispensing rates were low during the study period and included very low rates of insulin dispensing compared to the dispensing rates of these medicines in other countries in East Mediterranean Region or in Europe." (PMID 34645430, 2021). "Despite initially being managed with standard of care using current T2DM guidelines, including the use of insulin therapy, this cohort had suboptimal control of their diabetes and Class 3 obesity before starting the LCD intervention." (PMID 34458301, 2021). "Of the 77 patients included in the secondary analysis, 2 were using long-acting insulin therapy for diabetes control." (PMID 34300354, 2021). "It has been shown that curcumin can suppress weight gain, improve insulin sensitivity, and prevent the development of diabetes in rodents and in prediabetic subjects." (PMID 34371900, 2021). "The unphysiological delivery of external insulin into the subcutaneous tissue instead of directly into the liver as in the non-diabetes situation leads in low-carbohydrate diets to more or less lack of insulin in the liver with e.g., less IGF-1 stimulation." (PMID 34444784, 2021). "Following the newest American Diabetes Association ADA guideline, the early introduction of insulin should be considered if symptoms of hyperglycaemia are present or when HbA1c levels or blood glucose level are very high." (PMID 35177981, 2021). "Studies have also shown that hydroxycinnamic acid, a derivative of cinnamic acid, can improve glucose hemostasis and insulin resistance, thus helping in the prevention of diabetes complications." (PMID 34925813, 2021). "From the perspective of ameliorating diabetes, there are studies demonstrating that improved insulin secretion and insulin sensitivity as well as better control of blood glucose were observed after reducing the level of body iron storage." (PMID 34258295, 2021). "Loss or dysfunction of β-cells can lead to the release of insufficient insulin to cover the organism needs, promoting diabetes development." (PMID 33546109, 2021). "The leptin/ghrelin ratio correlated with BMI (r = 0.304, p = 0.018), ponderal status (r = 0.29, p = 0.021), diabetes presence (r = 0.318, p = 0.013), insulin (r = 0.287, p = 0.026), and patients’ sex (r = −0.404, p = 0.001)." (PMID 34829886, 2021). "Nevertheless, some work in this area has found a link between taking insulin and depression among patients with diabetes." (PMID 33803134, 2021). "The study inferred that insulin sensitizers, such as pioglitazone in combination with metformin, can induce diabetes remission in individuals with T2DM." (PMID 34842637, 2021).
diabetes (continued). "Diabetes mellitus (DM) is a metabolic disorder characterized by high levels of blood glucose due to defective insulin production, insulin action, or both." (PMID 34648514, 2021). "In a community-based cohort study, the results suggested that insulin sensitivity measured with euglycemic clamp was independently related to eGFR, and impaired insulin sensitivity might be associated with the development of early renal dysfunction before the onset of diabetes." (PMID 35174179, 2021). "Inhaled human insulin (Afrezza, Valencia, California) was approved in 2014 for adults with diabetes as an alternative prandial insulin." (PMID 37745178, 2021). "Type 2 diabetes mellitus is a metabolic disorder characterized by high blood glucose levels resulting from altered insulin secretion or action." (PMID 34068221, 2021). "Fully adjusted models for associations between physical activity and retinal photocoagulation stratified by gender, BMI, insulin used, family history of diabetes, hypertension and cardiovascular disease †." (PMID 33444338, 2021). "CircRNA has been reported to be involved in the regulation of insulin secretion and the pathogenesis of diabetes." (PMID 34272768, 2021). "It was also correlated with a poor evaluation of insulin care, and insulin-treated patients reported slightly higher diabetes pain relative to oral- or diet-treated patients." (PMID 33916851, 2021). "Type 2 diabetes mellitus (T2DM) is a metabolic condition marked by a prolonged hyperglycemic state caused by a combination of underlying defects, which include insulin tolerance in muscle and liver, and reduced insulin production by pancreatic beta cells." (PMID 34203048, 2021). "This type of bread can reduce blood glucose and postprandial insulin levels by 25%, thus being able to preserve the function of pancreatic insulin-secreting cells and prevent obesity and diabetes." (PMID 34444699, 2021). "IP insulin delivery recently raised interest in the diabetes community as a promising alternative to the conventional SC route thanks to its faster pharmacokinetics and pharmacodynamics." (PMID 34564415, 2021). "Thirty percent of participants were under diabetes management that included insulin, or both insulin and an oral hypoglycemic." (PMID 34827338, 2021). "On the other hand, because diabetes is a progressive disease with a decline in β-cell function, insulin use is one of the best or optimal choices for diabetic therapy for pancreatic dysfunction." (PMID 34457016, 2021). "Obesity, diabetes, insulin treatment, stress, and hypertension are words that attract the general public’s attention." (PMID 35046934, 2021). "In the Danish study, however, incidence of diabetes was defined as prescription redemptions of insulin or oral antidiabetic drugs, and ICD-10 diagnoses E10 or E11, while in the present study only diagnosis of E11 was analysed." (PMID 33724988, 2021). "T1D has a multimodal treatment, comprising insulin intensive therapy, diet therapy, physical exercise, self-monitoring, and diabetes education." (PMID 33672506, 2021). "Insulin therapy has effectively prevented diabetes development in several animal models by suspected metabolic and immunologic mechanisms." (PMID 33418839, 2021). "Available treatments for diabetes include bringing changes in lifestyle, relying on exercise, nutrition, oral medications, and insulin." (PMID 33849494, 2021). "Diabetes mellitus (DM) is a chronic metabolic condition characterized by persistent hyperglycemia due to insufficient insulin levels or insulin resistance." (PMID 35011414, 2021). "Societal beliefs about treatments, namely insulin, were also perceived as barriers to optimal diabetes management and important to consider when implementing." (PMID 34238258, 2021). "The technological approach has allowed more sophisticated insulin pumps, sensors, glucometers, capable of simplifying, and improving diabetes management." (PMID 33755854, 2021).
diabetes (continued). "Diabetes, a metabolic disorder induced by the modulation of insulin on glucose metabolism, is characterized by abnormal glucose homeostasis leading to elevated blood sugar and eventually resulting in damage to various organs of the body." (PMID 34394002, 2021). "The effects of STZ-induced diabetes and insulin on sodium and chloride-dependent GABA transport 2 (Gat2), which mediates the transport of BB for carnitine synthesis, were also determined." (PMID 34833964, 2021). "Participants free from incident pre-diabetes and type 2 diabetes also had lower glucose, insulin and HOMA-IR compared to those who did develop type 2 diabetes but not compared to those who developed prediabetes." (PMID 34309471, 2021). "Most diabetic patients receiving insulin suffer from episodes of hypoglycemia at least once per week, particularly after having narrow metabolic control in the management of their diabetes." (PMID 34067027, 2021). "These cells are accountable for producing insulin, and hence, a metabolic disturbance occurs due to increased glycemic levels and reduced insulin levels, similar to diabetes mellitus." (PMID 34577555, 2021). "A first report on critically ill subjects (among whom 7% with previously diagnosed insulin-treated diabetes) revealed that formerly insulin-treated diabetic individuals were more severely ill, however, they did not display an increased mortality rate." (PMID 33973089, 2021). "The discovery of insulin molecule, a ground-breaking innovation in the history of diabetes care, has completed 100 years in 2021." (PMID 34924015, 2021). "Local studies in Saudi children with diabetes showed that continuous subcutaneous insulin infusion improved glycemic control, with decreased hypoglycemic episodes and diabetic ketoacidosis events." (PMID 34395347, 2021). "It is distinguished by increased glucose uptake and the generation of fatty acids, which promotes insulin sensitivity and type 2 diabetes mellitus." (PMID 34067712, 2021). "Diabetes mellitus (DM) is defined as a metabolic disease characterized by hyperglycemia due to insulin secretion, insulin action, or a combination of both." (PMID 33869312, 2021). "The role of glucagon-like peptide 1 (GLP-1) in insulin-dependent signaling is well-known; GLP-1 enhances glucose-dependent insulin secretion and lowers blood glucose in diabetes." (PMID 33536884, 2021). "In two studies of paediatric patients with diabetes at diagnosis and after seven years, ICA512/IA2 persistence was associated with presence of C-peptide, better glycaemia and lower insulin requirement, suggestive of preserved beta cell function." (PMID 34083567, 2021). "Reactive oxygen species (ROS) can participate in the development of diabetes by altering the action of insulin and destroying the beta cells of the pancreas." (PMID 34691229, 2021). "By log transformation to both FI and FG in the denominator a correction for patients with diabetes mellitus type 2, where glucose is high and insulin is low, was established." (PMID 33588833, 2021). "FFA induces the inactivation of kinase proteins involved in the insulin signaling pathway by phosphorylation and leads to diabetes mellitus." (PMID 33921979, 2021). "Diabetes mellitus (DM) pertains to a range of metabolic disorders that are characterized by chronic hyperglycemia, coupled with insufficiencies and/or dysfunctional insulin secretion." (PMID 34361714, 2021). "Type 2 diabetes mellitus is a widespread medical condition, characterized by high blood glucose and inadequate insulin action, which leads to insulin resistance." (PMID 34445300, 2021). "AN severity correlates with the severity of IR, and AN fades when beta-cell decompensation occurs, leading to a decrease in insulin concentration and, ultimately, diabetes." (PMID 34841432, 2021).
diabetes (continued). "This previous study also found that patients in secondary care had a longer diabetes duration, used more insulin, had a higher prevalence of complications, a higher BMI and higher HbA1c levels." (PMID 33879081, 2021). "Myo-ins, being second messengers of insulin, exhibit an insulin sensitizing action, which explains the therapeutic use of this molecule in patients affected by insulin resistance and diabetes." (PMID 34445135, 2021). "In a nationwide observational cohort study conducted in England, insulin therapy, but also therapy with DPP-IV inhibitors have been linked to increased COVID-19 mortality in patients with type 2 diabetes mellitus." (PMID 34683125, 2021). "Allpatients were previously on insulin pump therapy and transitioned to the use of aHCL system to manage their diabetes." (PMID 34378426, 2021). "Of 40 participants, concerns included maintaining access to insulin (n=26, 65.0%), insulin delivery devices (n=15, 37.5%), blood glucose testing strips (n=17, 42.5%) and standard diabetes healthcare care reviews (n=25, 62.5%)." (PMID 35251446, 2021). "In comparison with metformin and sulfonylureas, insulin use has been shown to have more adverse outcomes in terms of diabetes-related complications, cardiovascular events, cancer, and all-cause mortality." (PMID 34458301, 2021). "Another study pointed out that inhibition or downregulation of CatG in non-obese diabetic mice reduced the activation of CD4+ T cells, improved the function of insulin-secreting β cells in the pancreas, and slowed down the progress of diabetes." (PMID 34869231, 2021). "In particular, patients with type 1 diabetes mellitus require insulin replacement therapy for life support and the regeneration of insulin-producing β-cells destroyed by autoantibodies and other factors for radical treatment." (PMID 34681566, 2021). "Rhesus monkeys also exhibit age-related clinical diabetes features including decreased insulin sensitivity and decreased insulin response to glucose challenge." (PMID 33860059, 2021). "Regarding medication use, 1 participant’s regimen included both oral diabetes medication and insulin, and the remaining 5 participants reported taking oral medication only." (PMID 34132640, 2021). "After recognizing the positive effect of insulin on cognitive status, and the harmful effect of insulin resistance on cognitive status, multiple studies were focused on the role of anti-diabetes medications in fighting dementia." (PMID 34877187, 2021). "The rat model of T2DM induced by HSFD and low-dose of STZ simulated the development of human diabetes mellitus (including insulin resistance and islet β cell dysfunction)." (PMID 34724560, 2021). "In concordance, the antenatal glucose at OGTT and insulin requirement during pregnancy, too, were predictors of metabolic syndrome, but most likely in first line are determinants for subsequent manifest diabetes pointing at beta cell dysfunction." (PMID 34078945, 2021). "One of these, the 1.1E7 remains to be tested regarding their sensitivity to certain diabetes-related toxic conditions in terms of apoptosis induction and insulin secretion dysfunction." (PMID 33806355, 2021). "Technology to support diabetes self-care has advanced significantly, including insulin pump therapy, continuous glucose monitoring, and sensor-augmented pump therapy, which are stepping stones toward the “artificial pancreas” using closed-loop technology." (PMID 34395347, 2021). "Only one clinical variable (complications of diabetes) was directly related to the absences of diabetic patients, albeit, we lack more insulin-treated patients in our study, so the impact of the type of treatment was not examined thoroughly." (PMID 34682989, 2021). "In this regard many drugs can modulate this ratio with therapeutic implications for patients with obesity and diabetes: insulin reduces ACE2 expression, but GLP-1 agonists, pioglitazone, ACE inhibitors, and statins upregulate ACE2, reducing the ACE/ACE2 ratio." (PMID 33648564, 2021).
diabetes (continued). "Some parents described how using insulin pumps and glucose sensors helped reduce the stresses and constraints diabetes management placed on everyday life." (PMID 33814007, 2021). "Type 2 diabetes mellitus is a metabolic derangement with abnormal reaction to insulin and β-cell dysfunction of the pancreas leading to unexplained weight loss, energy balance changes, retinopathy, neuropathy, nephropathy, and vascular complications." (PMID 34725640, 2021). "Diabetes is known as a metabolic disease that outcomes from failure in insulin action or insulin production or both." (PMID 34532035, 2021). "Among diabetes-free participants in ALSPAC, ABCG1 was positively associated with BMI, waist-circumference, fasting insulin, HOMA scores, CRP and triglyceride levels, but negatively associated with HDL levels." (PMID 33622391, 2021). "Despite significant advances in insulin-based and other therapies, patients with diabetes will continue to receive medication throughout their entire lives." (PMID 34445786, 2021). "People with type diabetes must take insulin; however, there is a globally agreed target to halt the rise in diabetes and other diseases by 2025." (PMID 33869633, 2021). "Diabetes mellitus is a chronic metabolic disease caused by insufficient insulin production (type 1 diabetes mellitus, T1DM) and/or a decrease in the tissue response to available insulin (type 2 diabetes mellitus, T2DM)." (PMID 34868060, 2021). "Given that 2021 marks the centenary of the discovery of insulin, there is need for global advocacy to ensure that the benefits of insulin and innovations in diabetes care reach all individuals living with diabetes." (PMID 33483763, 2021). "Despite these caveats, our promising results indicate that carnosine and β-alanine supplementation remain viable therapeutics to improve glycemic control and insulin resistance in diabetes and its related conditions." (PMID 34333586, 2021). "In fact, the use of an intranasal insulin spray developed as NasulinTM for the needle-free regimen of diabetes, was stopped after disappointing results in blood glucose control during a Phase 2a proof-of-concept clinical trial." (PMID 34834319, 2021). "Diabetes is a chronic metabolic disease in which the body cannot use or produce enough insulin efficiently, mainly related to genetic and environmental factors." (PMID 35126031, 2021). "Diabetes is a chronic metabolic disease characterized by elevated blood glucose levels due to insulin resistance and β-cell dysfunction." (PMID 33663065, 2021). "Metabolic Syndrome in Men (METSIM) study of the Finnish population was a large-scale study to evaluate the insulin sensitivity and insulin secretion over the entire range of fasting and two-hour plasma glucose, including diabetes." (PMID 34017668, 2021). "For example, escalation in medication treatment during a hospital stay, such as beginning insulin therapy, which has been identified as a significant predictor of 30-day readmission in a sample of patients with diabetes." (PMID 34070282, 2021). "They felt, however, that despite maximizing screening and insulin treatment, improvements in survival had “stalled” and that completely obliterating the survival discrepancy related to diabetes would require a different approach." (PMID 34926166, 2021). "The authors discovered a significant reduction in mortality at 1 year in the group that was assigned to insulin therapy, and distinguished newly diagnosed patients with diabetes from the ones with a prior history of the diagnosis." (PMID 33463901, 2021). "The interviews will explore parents’/guardians’ experiences of using closed-loop insulin delivery (as compared with sensor-augmented pump therapy) to manage their child’s diabetes." (PMID 33579766, 2021). "Given their role in regulation of glucose metabolism, β-cells are pivotal in the pathogenesis of diabetes mellitus (DM), a metabolic disorder characterized by insulin dysregulation and chronic hyperglycemia." (PMID 35173681, 2021).